TET1 (tet methylcytosine dioxygenase 1)
Diseases named in the same sentence as TET1 in open-access papers (continued):
Sharing a sentence is not in itself a finding about the gene and the disease.
pancreatic cancer (10 papers, 2016 to 2025). "In pancreatic cancer, TET1 levels and 5hmC content are downregulated, low levels of TET1 are associated with short overall survival, and TET1 acts as a tumor suppressor." (PMID 40599235, 2025). "A low level of TET1 expression was also associated with poor survival in pancreatic cancer patients." (PMID 36979633, 2023). "Pancreatic cancer patients with low TET1 expression levels have poorer overall survival compared with those with higher TET1 levels." (PMID 40520993, 2025). "As Wu et al63 outlined in 2019, TET1 acts as an inhibitor of pancreatic tumor progression and metastasis both in vivo and in vitro by suppressing Wnt signaling pathways." (PMID 40520993, 2025). "In pancreatic cancer cells, TET1 inhibited tumor growth by suppressing the WNT/β-catenin pathway by elevating the expression of SFRP2, an upstream inhibitor of the WNT/β-catenin pathway, via enhanced 5mC oxidation at its promoter." (PMID 36979633, 2023). "It is known from pancreatic cancer that a low TET1 expression and subsequent low 5hmC content lead to low survival of patients because of high tumor cell proliferation and metastasis." (PMID 34073664, 2021). "Pancreatic cancer patients with low TET1 expression levels have shorter survival rates than those with higher TET1 levels." (PMID 34656178, 2021). "Similar to CC, TET1 inhibits pancreatic cancer progression by blocking the Wnt signalling pathway and suppresses pancreatic tumour proliferation and metastasis in vivo and in vitro." (PMID 34656178, 2021). "Pancreatic cancer patients with high TET1 levels exhibit longer overall survival than patients with low levels of TET1." (PMID 32328088, 2020). "This is the first report of TET1 as a suppressor of pancreatic tumors, further elucidating the role of TET1 in pancreatic cancer." (PMID 31399111, 2019). "In this study, we determined the potential involvement of TET1 in pancreatic cancer progression, focusing on tumor proliferation and metastasis." (PMID 31399111, 2019). "Cell proliferation assay, wound-healing assays, transwell migration assay and nude mice model of orthotopic pancreatic cancer implantation were performed to assess the function of TET1 in pancreatic tumor." (PMID 31399111, 2019). "Survival analysis showed pancreatic cancer patients with low TET1 expression had shorter overall survival than patients with high TET1 levels." (PMID 31399111, 2019). "Aberrant DNA methylation in pancreatic tumors has been widely studied in recent years, while the relationship between TET1 and pancreatic cancer is still unclear, with only a decrease in 5-hmC levels reported by Yang." (PMID 31399111, 2019). "TET1 levels and 5-hmC content were downregulated in pancreatic tumor tissues and cell lines, and pancreatic tumor patients with low TET1 levels had a shorter overall survival than patients with high levels of TET1." (PMID 31399111, 2019). "Considering this result, we focused our subsequent research on the role of TET1 in pancreatic tumors." (PMID 31399111, 2019). "For therapy of pancreatic tumor patients with TET1 low expressing, our finds provide potential targets including TET1 and its downstream gene SFRP2 for therapy." (PMID 31399111, 2019). "TET1 is downregulated in pancreatic tumor tissues, and pancreatic tumor patients with low TET1 levels have shorter overall survival than patients with high levels of TET1." (PMID 31399111, 2019). "In this study, we investigated the role of TET1 in the progression of pancreatic tumor and its mechanism of tumor suppression." (PMID 31399111, 2019). "We found TET1 plays as a suppressor in pancreatic tumor progression via obstructing Wnt signaling pathways." (PMID 31399111, 2019). "In pancreatic tumors, we revealed that TET1 diminished β-catenin in both the nucleus and cytoplasm and disturbed the intracellular migration of active β-catenin." (PMID 31399111, 2019).
pancreatic cancer (continued). "To investigate the function of TET1 in pancreatic tumors, we selected SW1990 and BXPC-3 pancreatic cell lines for further study." (PMID 31399111, 2019). "We utilized RNA arrays to demonstrate that overexpression of TET1 inhibited pancreatic tumor epithelial-mesenchymal transition (EMT) by suppressing the Wnt/β-catenin signaling pathway, but not the Transforming growth factor (TGFβ) or NOTCH signaling pathways." (PMID 31399111, 2019). "We also revealed that TET1 inhibited proliferation of pancreatic tumors by inducing GO/G1 arrest in the cell cycle, although the underlying mechanism requires further study." (PMID 31399111, 2019). "We found TET1 was downregulated in pancreatic tumor tissues and cell lines, and that pancreatic tumor patients with low TET1 levels have shorter overall survival than patients with high levels of TET1." (PMID 31399111, 2019). "In our study, the inhibitory function of TET1 in pancreatic tumor proliferation was detected in vivo and in vitro." (PMID 31399111, 2019). "Moreover, CRISPR-Cas9-induced knockout of TET1 showed that TET1 suppress pancreatic cancer progression via inhibition of the Wnt pathway." (PMID 36048239, 2022). "Therefore, TET1 can suppress pancreatic tumor development by inhibiting proliferation and metastasis." (PMID 32328088, 2020). "We found TET1 was downregulated in pancreatic tumor tissue compared to adjacent non-tumor tissue in > 3/5 pancreatic cancer patients, and low expression of TET1 was associated with shorter overall survival." (PMID 31399111, 2019). "The expression of these markers indicates that TET1 reverses EMT progress in pancreatic cancer." (PMID 31399111, 2019). "TET1 suppressed pancreatic tumor proliferation and metastasis in vivo and in vitro." (PMID 31399111, 2019). "As TET1 is a demethylation enzyme, we hypothesized that pancreatic tumor suppressor genes could be involved in the anti-tumor activity of TET1." (PMID 31399111, 2019). "TET1 suppresses pancreatic tumor proliferation and metastasis." (PMID 31399111, 2019). "In this study, we first demonstrated the involvement of TET1 in pancreatic tumors." (PMID 31399111, 2019). "In addition, TET1 is involved in the development of drug resistance in pancreatic cancer." (PMID 40599235, 2025). "However the function of TET1 in pancreatic tumor remains poorly understood." (PMID 31399111, 2019). "IHC showed that TET1 was reduced in 35/57 pancreatic tumor tissues compared with adjacent non-tumor tissues, which was consistent with the mRNA level results." (PMID 31399111, 2019). "TET1 binds to the SFRP2 promoter and catalyzes demethylation to activate SFRP2 transcription, inhibiting the Wnt signaling pathway and ultimately obstructing EMT in pancreatic tumors." (PMID 31399111, 2019). "Quantitative real-time PCR (qRT-PCR), immunohistochemical (IHC) staining and dot blot were performed to detect the TET1 and 5-hmC expression in pancreatic tumor tissues and its adjacent non-tumor tissues." (PMID 31399111, 2019). "To analyze the correlation between TET1 expression levels and clinic-pathological parameters, we implemented a tissue array containing 63 pancreatic tumor tissues (57 of 63 had paired neighboring non-tumor tissues)." (PMID 31399111, 2019). "TET1 binds to the secreted frizzled-related protein 2 (SFRP2) promoter and catalyses its demethylation to activate SFRP2 transcription, thereby repressing the Wnt/β-catenin signalling pathway and ultimately restraining the epithelial-mesenchymal transition (EMT) in pancreatic tumours." (PMID 34656178, 2021). "TET1 bound to the secreted frizzled-related protein 2 (SFRP2) promoter and catalyzed demethylation to activate transcription of SFRP2, inhibiting both the canonical and non-canonical Wnt signaling pathways, and ultimately obstructing epithelial-mesenchymal transition (EMT) in pancreatic tumors." (PMID 31399111, 2019).
pancreatic cancer (continued). "Except TET1, other molecular mechanisms inhibiting Wnt signaling in pancreatic tumor like FOXO1-related LINC01197 has been reported, these mechanisms may contributes the final activity of Wnt signaling pathway in pancreatic tumor." (PMID 31399111, 2019).
fragile X syndrome (9 papers, 2020 to 2025). A genetic syndrome caused by mutations in the FMR1 gene which is responsible for the expression of the fragile X mental retardation 1 protein.
schizophrenia (8 papers, 2016 to 2025). A major psychotic disorder characterized by abnormalities in the perception or expression of reality. "TET1 (ten–eleven translocation methylcytosine dioxygenase 1) has NPAS3 (neuronal Per-Arnt-Sim 3) as a target that is associated with schizophrenia essential for synaptic plasticity in turn affecting learning and retention." (PMID 39299805, 2024). "We find that mice with Tet1 loss in the OL lineage exhibit impaired PPI and working memory deficits, two of the core symptoms related to schizophrenia." (PMID 34429415, 2021). "Since working memory deficits are characteristic features in schizophrenia, adult Tet1 cKO mice and control littermates at P90 were evaluated for their performance in the Morris water maze (MWM) to assess their working memory." (PMID 34429415, 2021). "In a human study, Tet1 mRNA and protein levels were upregulated in the brains of postmortem patients with schizophrenia compared with those of healthy controls." (PMID 27348532, 2016). "TET1's role in the context of schizophrenia and bipolar disorder is complex and may involve mechanisms that are independent of its DNA hydroxymethylation activity." (PMID 40520993, 2025). "The lost association of DDAH1 expression with CG promoter motif genes may mirror the overexpression of TET1 in cortical structures in patients with schizophrenia or bipolar disorder." (PMID 36233204, 2022). "Nevertheless, a study investigating an animal model of schizophrenia showed prenatal stress-decreased bdnf transcription in the frontal cortex and hippocampus was accompanied by the overexpression of Tet1 and increased 5 hmC enrichment at bdnf promoter regulatory regions." (PMID 27857218, 2016). "TET1 expression was increased, while APOBEC3A and APOBEC3C expression was decreased in the frontal cortex of schizophrenia patients, suggesting that the disruption of the DNA methylation and demethylation pathways may contribute to elevated 5hmC levels in schizophrenia patients." (PMID 38203806, 2024).
breast tumors (7 papers, 2017 to 2025). "Of clinical relevance, we first quantified the expression of GATA6 and TET1 in breast tumors and adjacent normal breast tissues." (PMID 40216762, 2025). "For example, in lines originating from solid tumors such as gastric, colorectal, hepatocellular, and breast tumors, apoptosis increased upon TET1 overexpression." (PMID 37371754, 2023). "3,6-DHF administration also promoted the levels of TET1 and 5hmC in xenografted breast tumors derived from MDA-MB-231 cells, confirming the effect of 3,6-DHF on TET1." (PMID 28870206, 2017). "Instead, the demethylating enzymes TET1, 2 and 3 did not present any difference associated with laterality in 1095 primary breast tumors (571 L and 524 R) (non-normally distributed data, Welch unpaired T-test, p > 0.05)." (PMID 35123413, 2022). "Furthermore, we found that 3,6-DHF administration promotes the levels of TET1 in xenografted breast tumors derived from MDA-MB-231 cells." (PMID 28870206, 2017). "Besides, hypoxia can induce the upregulation of TET1 and TET3 in breast tumor–initiating cells (BTIC), which is required to activate TNFα–p38–MAPK signaling that drives breast tumor malignancy." (PMID 38468288, 2024).
lung adenocarcinoma (7 papers, 2017 to 2025). A carcinoma that arises from the lung and is characterized by the presence of malignant glandular epithelial cells. "In lung adenocarcinoma, Pei et al58 discovered that TET1 formed a complex with methyl-CpG binding domain protein 2 (MBD2) to activate miR-200s, key regulators of tumor invasiveness." (PMID 40520993, 2025). "Our results are the first to demonstrate that TET1-mediated DNA hypomethylation regulates the expression of MUC4 in lung adenocarcinomas." (PMID 28680536, 2017). "The research of regarding TET1 as a potential therapeutic target has also made some progress, especially in T-ALL, TNBC and lung adenocarcinoma." (PMID 34656178, 2021).
lung fibrosis (7 papers, 2017 to 2024). "The induction of lung fibrosis by TET1 is mitigated by miR-302a-3p and miR-30a through the downregulation of TET1 expression via binding to the 3′-UTR of its mRNA." (PMID 39195573, 2024). "Exosomal miR-302a-3p from iPSCs hinders M2 polarization of macrophages via targeting ten-eleven translocation 1 (TET1), resulting in repressing BLM-induced lung fibrosis." (PMID 36979471, 2023). "Additionally, exosomes derived from induced pluripotent stem cells (iPSCs) suppress M2-type macrophages by delivering miR-302a-3p and silencing ten-eleven translocation 1 (TET1), thereby attenuating pulmonary fibrosis." (PMID 38655063, 2024).
depression (6 papers, 2020 to 2024). "Overall, our results stress the importance of distinguishing between the two isoforms in future studies and provide the impetus to reexamine previous findings related to TET1 in depression, addiction and bipolar disorder." (PMID 33262245, 2021). "Tet1 knockout (KO) in mice enhances long-term depression and impairs memory extinction, whereas Tet2 KO increases neural stem cell proliferation and reduces differentiation potential." (PMID 32466098, 2020). "Moreover, sodium butyrate was reported to improve aversive memory impairment, depression-like behaviors, and hippocampal microglial activation via inhibiting histone deacetylase and increasing the levels of Ten-Eleven Translocation 1 (TET1), 5-HT, and BDNF expression." (PMID 37759312, 2023).
myelodysplastic syndrome (6 papers, 2013 to 2024). A clonal hematopoietic disorder characterized by dysplasia and ineffective hematopoiesis in one or more of the hematopoietic cell lines. "However, TET2 was reported to play a regulatory role in myeloproliferative neoplasms and myelodysplastic syndromes in the form of functional deletion mutations, whereas TET1 and TET3 were rarely characterized of functional deletion mutations to function in hematological tumors." (PMID 32014008, 2020). "TET2 mutations frequently occur in AML, myelodysplastic syndromes (MDS) and chronic myelomonocytic leukemia (CMML), whereas TET1 and TET3 mutations rarely happen." (PMID 32209730, 2020). "TET2 mutations are frequent in patients with AML, myelodysplastic syndromes (MDS) and chronic myelocytic leukaemia (CML), while TET1 and TET3 mutations are rare." (PMID 34656178, 2021).
osteosarcoma (6 papers, 2019 to 2022). A usually aggressive malignant bone-forming mesenchymal neoplasm, predominantly affecting adolescents and young adults. "We used a pool of three specific guide RNAs (gRNAs) to direct a catalytically inactive Cas9 nuclease fused to the catalytic domain of TET1 (dCas9-TET1) to the last exon of the APOE gene in human osteosarcoma (U-2 OS) cells." (PMID 35191837, 2022). "In this study, TET1 was validated as a downstream target for miR-27a-3p in GC, and this demonstration is consistent with their relationship in osteosarcoma." (PMID 33088215, 2020). "In the meantime, the EMT marker gene Twist was significantly inhibited in circ‐0000190 overexpression and circ‐0000190‐EVs models, implying that perhaps TET1 plays a role in the pathogenesis of osteosarcoma through the modulation on the EMT process." (PMID 31923350, 2020). "Over-expression of Tet1 increased cell apoptosis and inhibited cell growth in osteosarcoma cells." (PMID 35155564, 2021). "The mRNA levels of TET1 were remarkably inhibited in osteosarcoma tumour tissues." (PMID 31923350, 2020). "Subsequently, TET1 expression in osteosarcoma cell line was determined via qRT‐PCR." (PMID 31923350, 2020). "HU regulated TET1 expression in the present study, suggesting that it might have a role in osteosarcoma." (PMID 30988069, 2019). "In addition, EVs circ‐0000190 may induce miR‐767‐5p to modulate TET1 and impede osteosarcoma progression." (PMID 31923350, 2020).
Alzheimer disease (5 papers, 2020 to 2025). A progressive, neurodegenerative disease characterized by loss of function and death of nerve cells in several areas of the brain leading to loss of cognitive function such as memory and language. "More intriguingly, TET1 deficiency in 5xFAD mice has been associated with increased plaque burden, thereby accelerating the progression of Alzheimer’s disease (Armstrong, Jin, Vattathil, Huang, Schroeder, Bennet, Qin, Wingo and Jin 2023)." (PMID 40133886, 2025). "Recently, scientists investigated the role of TET1 in Alzheimer's disease by examining TET1 mutations in individuals with early-onset Alzheimer's disease and identified significant associations." (PMID 40520993, 2025). "TET1 deficiency results in molecular changes in oocytes, including altered organelle function, disrupted ubiquitination and autophagy, and modifications in signaling pathways associated with Alzheimer's disease." (PMID 40520993, 2025). "In addition, many genes closely related to neurological diseases, such as Got1, ApoE, Gm2a, have been found to interact with TET1 in OPCs; and Cst3 is associated with dementia in Lewy body disease and Alzheimer's Disease." (PMID 32974003, 2020). "In conclusion, TET1 plays a therapeutically significant role in multiple disease models, such as acute kidney injury and Alzheimer’s disease, highlighting its notable research value and broad clinical application potential." (PMID 40133886, 2025). "Conclusion in PLGA nanocarriers curcumin solved the problem of its insolubility in water, and conjugation with Tet-1 made it possible to increase nanoparticles capture in the treatment of Alzheimer’s disease (AD)." (PMID 33202839, 2020). "Additionally, a mouse model with TET1 knockout was used, revealing increased Alzheimer's disease-related pathology, including amyloid plaque burden and changes in gene expression." (PMID 40520993, 2025). "Nevertheless, our findings that Tet1 may involve in autophagy, X-chromosome activation and Alzheimer’s disease provide additional insights into molecular basis of POF." (PMID 33834024, 2021).